TGFBR2 (transforming growth factor beta receptor 2)
Diseases named in the same sentence as TGFBR2 in open-access papers (continued):
Sharing a sentence is not in itself a finding about the gene and the disease.
lung carcinoma (continued). "A previous report showed that TGF-β enhanced the lethal effects of 5-FU in human lung cancer cells; this supports our in vitro data that IFN-α/5-FU-induced apoptosis was enhanced by TGFBR2 expression." (PMID 23457527, 2013). "Therefore, Hesperetin is of important value in research and application for treating lung cancer, especially for LUAD patients with abnormal TGFBR2 expressions." (PMID 39364312, 2024). "In this matter, TGFBR2 has recently been proposed as a tumor suppressor with prognostic value in early-stage NSCLC; however, there is no prior evidence of an association between KLF13 and lung cancer prognosis, so further research is required." (PMID 36900258, 2023). "TGFBR2, FLI1, ERG and NTRK3 were shared DEmRNAs of hsa‐mir‐9‐1, hsa‐mir‐9‐2 and hsa‐mir‐9‐3, which suggested that mir‐9 might play a crucial role in LUAD by regulating these four lung cancer‐related genes." (PMID 30761256, 2019). "CXCL12, CK7, CDH1, CTNNB1, TGFBR2 and CD44v6 were upregulated in CTC as well as cfRNA whereas all these genes were downregulated in exosomes of primary lung cancer with and without metastasis." (PMID 38877052, 2024). "Quantitative gene expression patterns of CXCL12, CK7, CDH1, CTNNB1, HIF1A, MUC16, TGFBR2 and CD44v6 were analyzed from CTC, exosomes and cell free RNA of lung cancer patients with and without liver metastasis." (PMID 38877052, 2024).
Loeys-Dietz syndrome (37 papers, 2007 to 2025). Loeys-Dietz syndrome is a rare genetic connective tissue disorder characterized by a broad spectrum of craniofacial, vascular and skeletal manifestations with four genetic subtypes described forming a clinical continuum. "Here we report an individual 22.1 with a heterozygous missense variant in the TGFBR2 NM_003242.6:c.1561T>C; p.(Trp521Arg) and diagnosed with Loeys-Dietz syndrome including hypoplastic amelogenesis imperfecta." (PMID 37228816, 2023). "The locus contains TGFBR2, a gene of which pathogenic variants are the cause for 25% of cases of Loeys Dietz syndrome, which predisposes mainly to thoracic aortic aneurysms but also to IA." (PMID 35228681, 2022). "Further, humans with a mutation in TGFBR2 exhibit Loeys Dietz syndrome, of which a main symptom is sleep apnea." (PMID 34777213, 2021). "For instance, mutations in either TGF-β receptor type I (TGFBR1) or type II (TGFBR2) are associated with Loeys-Dietz syndrome." (PMID 31241461, 2019). "Defects in TGFBR2 can result in serious debilitating and fatal diseases in humans, most notably the autosomal dominant aortic aneurysm syndrome, Loeys-Dietz syndrome, as well as an increased risk of certain cancers." (PMID 28100171, 2017). "Mutations in TGFBR2 have also recently been identified in patients with Loeys-Dietz syndrome, and familial thoracic aortic aneurysms." (PMID 22259224, 2012). "Heterozygous missense variants in TGFBR2 are well established to cause Loeys-Dietz Syndrome." (PMID 40489498, 2025). "Also, PERADIGM identified TGFBR2 gene associated with Loeys-Dietz syndrome, which has overlapping cardiovascular and skeletal manifestations with Marfan syndrome." (PMID 41411243, 2025). "Our family also suggests that all the constitutive features of Loeys-Dietz syndrome may be missing in large families with a P/LP TGFBR2 variant." (PMID 41310652, 2025). "Heterozygous mutations in the genes encoding TGF-β receptors 1 and 2 (TGFBR1 and TGFBR2, respectively) cause Loeys-Dietz syndrome, an autosomal dominant aortic aneurysm syndrome, which predisposes patients to aggressive vascular disease with widespread systemic involvement." (PMID 35234888, 2022). "In addition, mutations in the TGF-β receptor genes (TGFBR1 and TGFBR2) result in Marfan-like syndromes with aortic aneurysms and dissections as well, named ‘Loeys-Dietz Syndrome’." (PMID 25238161, 2014). "Tgfbr2 mutations are associated with the human disease Loeys Dietz syndrome." (PMID 22745736, 2012). "This conditional ablation of Tgfbr2 also leads to skull defects which are also seen in Loeys-Dietz Syndrome patients." (PMID 40489498, 2025). "Vascular Ehlers-Danlos syndrome, resulting from mutations in the COL3A1 gene, and Loeys-Dietz syndrome, linked to TGFBR1 and TGFBR2 mutations, are known to predispose individuals to arterial dissections due to connective tissue fragility." (PMID 41362507, 2025). "Among the genes queried, COL3A1 and aggregated testing of Loeys-Dietz syndrome-associated genes (TGFBR1, TGFBR2, SMAD2, SMAD3, TGFB2, TGFB3) were the leading signals of enrichment, consistent with prior studies [21•, 24, 25]." (PMID 37979122, 2023). "TGFBR1/2 and SMAD2/3 encode proteins involved in TGF-β signaling and mutations in these genes cause Loeys-Dietz syndrome (LDS) in patients (TGFBR1; LDS1; MIM 609192, TGFBR2; LDS2; MIM 61068, SMAD2; LDS6; MIM 619656, SMAD3; LDS3 (AOS); MIM 613795)." (PMID 35492343, 2022). "Loeys-Dietz syndrome, caused by mutations in TGFBR1 and TGFBR2, is characterized by vascular and skeletal abnormalities and arterial tortuosity, aneurysms and aortic dissection are the common presentations." (PMID 35414028, 2022).
Loeys-Dietz syndrome (continued). "A therapeutic effect of rapamycin on aortopathies has been reported in mice with Tgfbr2 disruption in postnatal SMCs, a model of Loeys-Dietz syndrome." (PMID 32397282, 2020). "Our high prevalence of mitral valve prolapse in Loeys-Dietz syndrome confirmed findings in a previous series of TGFBR1- and TGFBR2 pathogenic variants." (PMID 31795342, 2019). "The initial description of Loeys-Dietz syndrome reported pathogenic variants in the genes encoding for the transforming growth factor beta receptor 1 (TFGBR1) and 2 (TGFBR2)." (PMID 31795342, 2019). "A surgical series of Loeys-Dietz syndrome confirmed high rates of proximal aortic surgery, where 18% with TGFBR1, 48% with TGFBR2, and 27% with SMAD3 pathogenic variants underwent surgery." (PMID 31795342, 2019). "Within the Loeys-Dietz syndrome group, mean freedom from death was similar with TGFBR1 (70 ± 3 years, 95% CI 64–77), TGFBR2 (73 ± 5 years, 95% CI 63–83), and SMAD3 pathogenic variants (76 ± 6 years, 95% CI 64–89; p = 1.000)." (PMID 31795342, 2019). "Within the Loeys-Dietz syndrome group, mean freedom from proximal aortic surgery was similar with TGFBR1 (48 ± 5 years, 95% CI 38–58), TGFBR2 (49 ± 5 years, 95% CI 39–58), and SMAD3 pathogenic variants (68 ± 6 years, 95% CI 55–80; p = 0.143)." (PMID 31795342, 2019). "These include syndromic diseases associated with aortic aneurysms, including Marfan’s and Loeys Dietz Syndromes (LDS), due to mutations in TGFβ signaling genes FBN1, TGFBR1, TGFBR2, TGFB2, and TGFB3." (PMID 30307970, 2018). "Mutations in SMAD3, have been identified in up to 2% of patients with familial thoracic aneurysms leading to acute aortic dissection Patients with the Loeys-Dietz syndrome have mutations in receptors for TGF-β (TGFBR1 and TGFBR2)." (PMID 26925344, 2016). "Among these, Loeys-Dietz syndrome (MIM # 609,192) shows mutations in other genes which are involved in the same pathway of FBN1 and include TGFBR1 (MIM * 190,181), TGFBR2 (MIM * 190,182), SMAD3 (MIM * 603,109), TGFB2 (MIM * 190,220), TGFB3 (MIM * 190,230) and SMAD2 (MIM * 601,366)." (PMID 39008115, 2024). "Similarly, while TGFBR1- and TGFBR2-related Loeys-Dietz syndrome are included in the IUIS gene list for IEI, SMAD3-related Loeys-Dietz syndrome is not, despite manifesting with many of the same symptoms." (PMID 37215141, 2023). "Variants in TGFBR2 have been reported to be associated with Loeys-Dietz syndrome 2 (MIM 610168), colorectal cancer-hereditary nonpolyposis type 6 (MIM 614331), and esophageal cancer (MIM 133239)." (PMID 36672844, 2022). "Within the Loeys-Dietz syndrome group, freedom from distal aortic repair was lower with pathogenic variants in the TGFBR2 gene (p = 0.036; mean freedom from distal repair was not calculated because all cases were censored)." (PMID 31795342, 2019). "Therefore, we performed this observational case-matched comparison of a Loeys-Dietz syndrome group including 83 individuals with a pathogenic variant in the three most common genes identified in Loeys-Dietz syndrome (TGFBR1, TGFBR2, and SMAD3) gene." (PMID 31795342, 2019). "TGFBR2 mutations may cause a loss in function of TbRII and lead to MFS2, Loeys-Dietz Syndrome and Type 2 Thoracic aortic aneurysms and dissections." (PMID 22259224, 2012). "Among them, 51 patients had genetically confirmed HTAD (Marfan syndrome (FBN1), Loeys-Dietz syndrome (TGFBR1, TGFBR2, SMAD3, TGFB2), vascular Ehlers-Danlos syndrome (COLSA1), and non-syndromic HTAD (ACTA2, MYH11, MYLK))." (PMID 41310758, 2025).
Marfan syndrome (34 papers, 2005 to 2025). A disorder of the connective tissue. "This large family was instrumental in demonstrating the genetic heterogeneity of what was then known as “Marfan syndrome”, and subsequently in recognising the role of TGFBR2 variants in hereditary thoracic aortic disease." (PMID 41310652, 2025). "This family was originally described and treated as having Marfan syndrome, while other TGFBR2 variants have been associated with specific phenotypic features." (PMID 41310652, 2025). "One individual was heterozygous for the TGFBR2 p.Pro129fs (LP) variant associated with Loeys–Dietz syndrome, while a LP variant related to Marfan Syndrome (FBN1 p.Arg165Gln) was detected in another individual." (PMID 40970488, 2025). "Mutations in TGFBR1 or TGFBR2 genes have been reported in some patients with atypical presentation but nevertheless consistent with Marfan syndrome." (PMID 36873395, 2023). "In yet another instance, both in silico and in vitro functional analyses of a TGFBR2 VUS with a clinical diagnosis of Marfan syndrome confirmed the pathology of the variant and suggested the diagnosis of a very similar syndrome, Loeys–Dietz syndrome." (PMID 37895204, 2023). "It is interesting to mention that mutations in the TGFBR2 gene are associated with Marfan syndrome and Loeys-Deitz syndrome." (PMID 35757474, 2022). "For example, genetic variants in transforming growth factor beta (TGF-β) receptors type 1 (TGFBR1) and type 2 (TGFBR2) genes are commonly found in Marfan syndrome and can also be associated with patent ductus arteriosus and VSDs." (PMID 30257432, 2018). "Heterozygous mutations in TGFBR2 play an important role in Marfan syndrome, which is an extracellular matrix disorder with cardinal manifestations in the eye, skeleton, and cardiovascular systems." (PMID 30154914, 2018). "A disease that has many similarities with Marfan syndrome, termed Loeys-Dietz syndrome, was identified to be caused by variants in the transforming growth factor-beta type II receptor (TGFBR2)." (PMID 24941995, 2014). "Transforming growth factor beta receptor II (TGFBR2) gene mutations are associated with Marfan syndrome; however, the relationship between the mutations and clinical phenotypes are not clear." (PMID 22259224, 2012). "Recently, mutations in the human TGFBR2 gene have been reported to cause Marfan's syndrome, a disorder also associated with defective extracellular-matrix synthesis." (PMID 16403239, 2005). "Upon review of the medical record, genetics referrals, and genetic testing results, one individual was found to have Loeys–Dietz syndrome with a pathogenic variant in TGFBR2 (c.1591G>A, p.Ala531Thr), and one individual had a clinical diagnosis of Marfan Syndrome." (PMID 32887874, 2020). "The findings extend the mutation spectrum of Marfan syndrome, and that mutations at the F-helix in the kinase domain of TGFBR2 may be associated with the development of severe cardiovascular and skeletal lesions and minor ocular lesions." (PMID 22259224, 2012). "Recent studies show that genetic heterogeneity exists in MFS individuals, and transforming growth factor beta receptor II (TGFBR2) gene mutations have been identified in a subset of patients with MFS – which was termed as type 2 Marfan syndrome (MFS2)." (PMID 22259224, 2012). "While FBN1 mutations are the main cause, other genes have been implicated in Marfan syndrome and Marfan-like conditions, including TGFBR1 and TGFBR2." (PMID 41411243, 2025). "A more comprehensive understanding of the disease would require detailed genetic characterization beyond FBN1, including TGFB2, its receptors (TGFBR1, TGFBR2), and other genes involved in Marfan syndrome and related disorders." (PMID 40243722, 2025). "Mutations in TGFBR2 disrupt the TGF-β signaling pathway, which is essential for connective tissue maintenance and repair, leading to clinical features that can resemble Marfan syndrome." (PMID 41411243, 2025).
Marfan syndrome (continued). "We compared clinical manifestations and outcomes both between the Loeys-Dietz syndrome versus Marfan syndrome groups, and within the Loeys-Dietz syndrome group according to the pathogenic variant in the TGFBR1, TGFBR2, and SMAD3 gene." (PMID 31795342, 2019). "Mutations to transforming growth factor-beta receptor 2 (TGFβR2) in patients with Marfan's syndrome type II (MFS2 mapped at 3p24.2-p25) have demonstrated alternative evidence for abnormal TGF-β signaling in the pathogenesis of Marfan's syndrome." (PMID 21308160, 2010). "Compare to Marfan syndrome carrying FBN1 mutation, MV involvement is less frequent in LDS type 2: MVP was found in 21 vs. 45% of patients (P = 0.001), MR in 35 vs. 56% (p < 0.0001) and referral to MV surgery was rare in TGFBR2 patients." (PMID 36873395, 2023). "Marfan syndrome (MFS) is associated with FBN1 mutations; Ehlers–Danlos syndrome (EDS) is relevant to the COL3A1 mutation; Loeysؘ–Dietz syndrome (LDS) is related to TGFBR1 or TGFBR2 mutations as well as SMAD3 or TGFB2 mutations." (PMID 36291545, 2022). "We obtained a molecular diagnosis in 45/53 (85%) index patients, in which 36/53 (68%) had rare variants in FBN1 (Marfan syndrome; 63 patients in total), seven (13.3%) in TGFBR1/TGFBR2 (Loeys–Dietz syndrome; nine patients in total) and two patients (3.7%) in SKI (Shprintzen–Goldberg syndrome)." (PMID 33436942, 2021). "This speculation is supported by previous findings where the postnatal disruption of the Tgfbr2 gene expression was associated with decreased canonical TGF-β1 signalling and accelerated aneurysm growth in a murine model of Marfan syndrome." (PMID 28399937, 2017). "Marfan syndrome (MFS) is a multisystem disorder caused by mutations in the FBN1 gene and, to a lesser extent, in TGFBR2." (PMID 40565081, 2025). "Causative genes include autosomal polycystic kidney disease (PKD1, PKD2), Ehlers–Danlos syndrome (COL3A1), Marfan syndrome (FBN1), Loeys–Dietz syndrome (TGFB2, TGFB3, TGFBR1, TGFBR2, SMAD2, SMAD3), and Majewski Osteodysplastic Primordial Dwarfism (PCNT)." (PMID 40004483, 2025). "In the UK Biobank dataset, there was no overlap between Marfan syndrome patients and TGFBR2 rare LoF carriers, preventing traditional binary-based methods from detecting this association." (PMID 41411243, 2025). "Therefore, our objective was to assess the mRNA expression of FBN1, TGFBR1, TGFBR2, and TGFB2 in the aortic tissue of Marfan syndrome patients with aortic dilation." (PMID 40243722, 2025). "The best characterized genes include FBN1 [Marfan syndrome (MFS)], TGFBR1 and TGFBR2 [Loeys-Dietz syndrome (LDS)], SMAD3 [aneurysm-osteoarthritis syndrome (AOS)], and ACTA2 [Aortic and Cerebral Aneurysm (ACA)]." (PMID 36312254, 2022).
gastric cancer (31 papers, 2002 to 2025). A primary or metastatic malignant neoplasm involving the stomach. "TGFBR2(The type II transforming growth factor β receptor gene) was frequently frameshift mutated in several cancer types, especially in colorectal, endometrium, and gastric cancer cells." (PMID 36051999, 2022). "In addition, we found QKI, which is a tumor suppressor that is associated with cancer prognosis in gastric cancer, and TGFBR2, which is also associated with driver and susceptibility in gastric cancer." (PMID 32127608, 2020). "Previous studies have shown that ITGB5 promotes SNX17-mediated endosomal recycling of transforming growth factor beta receptor type 2 (TGFBR2), which enhances gastric cancer metastasis." (PMID 40303303, 2025). "When TGFBR2 expression was restored in miR-204-overexpressing gastric cancer cells, they regained resistance to 5-FU treatment." (PMID 37844011, 2023). "Downregulation of tumor suppressor Tgfbr2 expression in gastric organoids through retroviral delivery of Tgfbr2 shRNA produced various gastric cancer subtypes." (PMID 33459801, 2021). "Another way of driving cell proliferation and migration has been described through the overexpression miR-130a and suppressing TGFBR2 expression in gastric cancer." (PMID 33023154, 2020). "In this study, we found that TGFBR2 protein levels were consistently upregulated in gastric cancer tissues, whereas TGFBR2 mRNA levels varied among these tissues, indicating that a post-transcriptional mechanism is involved in the regulation of TGFBR2." (PMID 27120811, 2016). "The cancer-suppressive function of TGFBR2 was further confirmed in gastric cancer cells through the silencing and overexpression of TGFBR2." (PMID 27120811, 2016). "Subsequently, we provide experimental evidence that TGFBR2 possesses a tumor-suppressive function in gastric cancer and that the protein expression of TGFBR2 was directly suppressed by miR-17-5p in gastric cancer." (PMID 27120811, 2016). "Compared with the normal adjacent tissues, the TGFBR2 protein levels were dramatically downregulated in gastric cancer tissues." (PMID 27120811, 2016). "MiRNAs and the dysregulation of TGFBR2 are both known to be related to carcinogenesis and progression in gastric cancer." (PMID 27120811, 2016). "The results of our study depict a novel regulatory network in gastric cancer mediated by miR-17-5p and TGFBR2 and offer potential therapeutic targets in gastric cancer." (PMID 27120811, 2016). "To conclude, miR-17-5p promoted cell proliferation and migration by targeting TGFBR2 in gastric cancer." (PMID 27120811, 2016). "Given the metastasis-specific, biallelic alteration of TGFBR2, we exploited our validated primary air-liquid interface murine gastric organoid system to investigate if TGFBR2 knockdown was sufficient to induce gastric cancer metastasis." (PMID 25315765, 2014). "We demonstrate the functional validation of candidate gastric cancer metastasis drivers from cancer genomic profiling studies, focusing on modeling the TGFBR2 driver as proof of principle." (PMID 25315765, 2014). "For example, lentiviral delivery of shRNA against anti-inflammatory TGFbR2 in gastric cancer organoids led to metastatic differentiation and the acquisition of genetic heterogeneity, indicating that cancer-associated mutations in Tgfbr2 drive tumor progression." (PMID 29883385, 2018). "The expression of TGFBR2 in six pairs of human gastric cancer tissues and paired noncancerous tissues was first evaluated by western blotting assay to determine the expression patterns of TGFBR2 in human gastric cancer tissues." (PMID 27120811, 2016). "An inverse correlation between miR-17-5p and TGFBR2 protein was observed in gastric cancer tissues." (PMID 27120811, 2016). "We wondered whether a relationship exists between miRNAs and TGFBR2 regulation and what its biological effects on gastric cancer might be." (PMID 27120811, 2016).